HSD11B1 (hydroxysteroid 11-beta dehydrogenase 1)
Description:
Controls the reversible conversion of biologically active glucocorticoids such as cortisone to cortisol, and 11-dehydrocorticosterone to corticosterone in the presence of NADP(H). Participates in the corticosteroid receptor-mediated anti-inflammatory response, as well as metabolic and homeostatic processes. Plays a role in the secretion of aqueous humor in the eye, maintaining a normotensive, intraocular environment. Bidirectional in vitro, predominantly functions as a reductase in vivo, thereby increasing the concentration of active glucocorticoids. It has broad substrate specificity, besides glucocorticoids, it accepts other steroid and sterol substrates. Interconverts 7-oxo- and 7-hydroxy-neurosteroids such as 7-oxopregnenolone and 7beta-hydroxypregnenolone, 7-oxodehydroepiandrosterone (3beta-hydroxy-5-androstene-7,17-dione) and 7beta-hydroxydehydroepiandrosterone (3beta,7beta-dihydroxyandrost-5-en-17-one), among others. Catalyzes the stereo-specific conversion of the major dietary oxysterol, 7-ketocholesterol (7-oxocholesterol), into the more polar 7-beta-hydroxycholesterol metabolite. 7-oxocholesterol is one of the most important oxysterols, it participates in several events such as induction of apoptosis, accumulation in atherosclerotic lesions, lipid peroxidation, and induction of foam cell formation. Mediates the 7-oxo reduction of 7-oxolithocholate mainly to chenodeoxycholate, and to a lesser extent to ursodeoxycholate, both in its free form and when conjugated to glycine or taurine, providing a link between glucocorticoid activation and bile acid metabolism. Catalyzes the synthesis of 7-beta-25-dihydroxycholesterol from 7-oxo-25-hydroxycholesterol in vitro, which acts as a ligand for the G protein-coupled receptor (GPCR) Epstein-Barr virus-induced gene 2 (EBI2) and may thereby regulate immune cell migration.
Synonyms: 11-DH; 11-beta-HSD1; HSD11; HSD11L; SDR26C1; CORTRD2; HDL; HSD11B
Tractability: Small molecule: an approved drug acts on it; a structure with a bound ligand is known; a high-quality ligand is known; it has a high-quality binding pocket; it belongs to a druggable protein family. Antibody: UniProt predicts a signal peptide or a membrane-spanning region. PROTAC: its protein half-life has been measured; a small molecule that binds it is known.
Target class: Enzyme; Oxidoreductase
Chemical probes: AZD-4017 (high quality), CHEMBL1829763, PD005619, PD084354
Gene: Protein-coding gene on chromosome 1 (209,686,178 to 209,734,949, forward strand). Ensembl gene ENSG00000117594.
Subcellular location: Endoplasmic reticulum membrane
Pathways (Reactome):
Drug ADME: Prednisone ADME
Metabolism: Glucocorticoid biosynthesis
Gene Ontology:
Molecular function: 11-beta-hydroxysteroid dehydrogenase (NADP+) activity; NADP binding; protein homodimerization activity; steroid binding; 7-beta-hydroxysteroid dehydrogenase (NADP+) activity; carbonyl reductase (NADPH) activity; cortisol dehydrogenase (NADP+) activity
Biological process: steroid catabolic process; glucocorticoid catabolic process
Cellular component: endoplasmic reticulum membrane; membrane; endoplasmic reticulum
Genetic constraint (gnomAD): Loss-of-function variants: 13 observed, 21.2 expected, observed/expected ratio (o/e) 0.61, 90% interval 0.4 to 0.98. The upper end of that interval is the gene's LOEUF score, 0.98, which puts it in group 4 of 6, group 1 being the genes least tolerant of losing a copy. Missense variants: 279 observed, 369.99 expected, observed/expected ratio (o/e) 0.75, 90% interval 0.68 to 0.83. Synonymous variants: 121 observed, 131.02 expected, observed/expected ratio (o/e) 0.92, 90% interval 0.8 to 1.07.
Homologues: Orthologues: chimpanzee HSD11B1 (99% identical), macaque HSD11B1 (96% identical), pig HSD11B1 (83% identical), dog HSD11B1 (83% identical), mouse Hsd11b1 (78% identical), guinea pig HSD11B1 (74% identical), rabbit HSD11B1 (73% identical), tropical clawed frog hsd11b1l.2 (42% identical), Caenorhabditis elegans dhs-30 (25% identical), Caenorhabditis elegans T25G12.13 (25% identical), Drosophila melanogaster CG7601 (22% identical), Drosophila melanogaster CG31546 (21% identical), and 12 more. Paralogues in human: HSD11B1L (43% identical), DHRS7 (25% identical), DHRS7B (23% identical), DHRS4 (22% identical), RDH8 (22% identical), DHRS2 (21% identical), DHRS7C (21% identical), DHRS4L2 (18% identical), DHRS11 (18% identical), HSDL2 (18% identical), CBR1 (17% identical), CBR3 (16% identical), and 1 more.
Diseases named in the same sentence as HSD11B1 in open-access papers:
HSD11B1 is named in the same sentence as 100 diseases in open-access papers, as found by Europe PMC text mining. Sharing a sentence is not in itself a finding about the gene and the disease. The quoted sentences say what the papers report.
Obesity (41 papers, 2005 to 2025). Accumulation of substantial excess body fat. "Complementary bioinformatics analysis revealed four key targets associated with obesity onset: HSD11B1, RXRG, G6PD and PIK3R1." (PMID 41032481, 2025). "Specifically, obesity is associated with increased HSD11B1 activity in subcutaneous adipose tissue resulting in increased cortisone to cortisol conversion." (PMID 38560025, 2024). "HSD11B1 is highly expressed in abdominal adipose tissue, and its polymorphisms are closely related to obesity, metabolic syndrome, and diabetes." (PMID 38338442, 2024). "Association of HSD11B1 polymorphic variants and adipose tissue gene expression with metabolic syndrome, obesity and type 2 diabetes mellitus: a systematic review." (PMID 28443133, 2017). "In humans HSD11B1 hyperexpression has been associated with abnormal glucose metabolism and obesity in several studies." (PMID 28443133, 2017). "Many researches proved that the HSD11B1 linked to various metabolic abnormalities and the importance has been testified in obesity and insulin resistance and other components of the metabolic syndrome." (PMID 26452272, 2015). "Observational studies (cross-sectional, cohort, or case–control) which have analyzed the relationship of polymorphisms and/or HSD11B1 gene expression with obesity, MetS, or T2DM in human adults were considered eligible." (PMID 26056536, 2015). "Nine studies analyzed the association between 26 different HSD11B1 polymorphic variants and obesity, MetS, and T2DM." (PMID 26056536, 2015). "The inclusion criteria were observational studies (cross-sectional, cohort, or case–control), conducted in adults, which analyzed the relationship of HSD11B1 polymorphisms and/or HSD11B1 expression in abdominal adipose tissue with obesity, MetS, or T2DM." (PMID 26056536, 2015). "Nine studies analyzed the association of 26 different HSD11B1 polymorphic variants with obesity, MetS, and T2DM." (PMID 26056536, 2015). "HSD11B1 is well-known to play a pathogenic role in obesity, the metabolic syndrome and type 2 diabetes mellitus, and HSD11B1 inhibitors are currently being studied in both animals and humans as possible pharmacotherapies." (PMID 24643011, 2014). "Over 150 articles describe an association of Hsd11β1 with diabesity, and an intronic Hsd11b1 polymorphism is associated with obesity and insulin resistance in children." (PMID 15760467, 2005). "The LASSO regression models were built from data from obese and normal tissues, and the λ analysis indicated that the model achieved optimal predictive accuracy for obesity at λ = 4, leading to the identification of 4 core diagnostic genes, including HSD11B1, RXRG, G6PD and PIK3R1." (PMID 41032481, 2025). "As expected, the frequency of obesity was lower among individuals carrying at least three minor alleles of HSD11B1 rs45487298:delA>insA and H6PD rs6688832:G>A polymorphisms than in the group of individuals with fewer than three minor alleles (24.4% vs. 41.6%, respectively; P = 0.033)." (PMID 31558916, 2019). "The decreased activity of HSD11B1 in the liver among individuals with obesity has been suggested to be caused by chronic hyperinsulinemia, whereas the sustained hepatic HSD11B1 activity among patients with type 2 diabetes may be caused by insulin resistance and a relative insulin deficiency." (PMID 32069218, 2020). "For example, mulberry leaf extract has been shown to alleviate obesity by upregulating Hsd11b1 expression in WAT, thereby modulating lipid metabolism and inflammatory pathways." (PMID 41019552, 2025). "There is mounting evidence for a pathological role of glucocorticoids and HSD11B1 in obesity and metabolic syndrome." (PMID 38560025, 2024). "Some of the well-known obesogenic or obesity marker genes, such as Hsd11b1 and Lep, were obviously upregulated by OVX, while some of the well-known fatty acid oxidation genes, e.g., Ucp1 were downregulated by OVX." (PMID 37834368, 2023).
Obesity (continued). "Inactive cortisol is converted into active cortisol under the action of enzyme 11-β hydroxysteroid dehydrogenase type 1 (HSD11B1), thereby promoting the occurrence of obesity." (PMID 37398946, 2023). "Recently, an RNA-Seq study was performed to explore the effects of castration on fat deposition in different parts of pigs and HSD11B1 was reported as a factor affects glucose uptake by adipocytes and leads to obesity." (PMID 37252399, 2023). "The conversion of cortisone to cortisol by HSD11B1 is regulated by several factors related to obesity and type 2 diabetes." (PMID 32069218, 2020). "Obesity-related genes were retrieved in the Digsee database and the top 15 obesity-related genes were selected as disease genes (Adipoq, Igf1, Fto, Hsd11b1, Tnf, Gh1, Mc4r, Lep, Pparg, Il6, Crp, Lepr, Pomc, Lpl, and Ghr1)." (PMID 31060494, 2019). "The relationship of HSD11B1 rs45487298 and H6PD rs6688832 polymorphisms with obesity and MetS was studied." (PMID 31558916, 2019). "The results of the present study suggest that HSD11B1 abdominal adipose tissue expression in participants with obesity and/or MetS decreases in order to compensate increased HSD11B1 activity." (PMID 31558916, 2019). "Transgenic mice overexpressing HSD11B1 develop visceral obesity and exhibited insulin-resistant diabetes and dyslipidemia, while HSD11B1-knockout mice are protected from the adverse metabolic complications of obesity and high fat diet-induced hyperglycemia." (PMID 31558916, 2019). "When stratifying the sample either by the presence of obesity or MetS, in both groups we have found an inverse relationship between abdominal adipose tissue HSD11B1 gene expression and BMI, but this relationship remained significant only in those with obesity." (PMID 31558916, 2019). "It has been reported that too much cortisol or overexpression of HSD11B1 induces obesity and the insulin resistance that accompanies metabolic syndrome in rodent adipose tissue." (PMID 29206210, 2017). "Lastly, obesity networks (e.g., transcripts including Retn, Lpl, Lep, Esr1, Lipc, Hsd11b1, Gpt, Lipe, Vldlr, and Il6, among others, fold change −1.042, P < 0.05) were also decreased by 4% (1.04-fold)." (PMID 28446880, 2017). "Twenty one studies assessed the potential relationship of HSD11B1 expression in subcutaneous and visceral abdominal fat with obesity." (PMID 26056536, 2015). "This systematic review included 32 studies which analyzed the potential relationship of abdominal adipose HSD11B1 gene expression in human and its polymorphic variants with MetS, T2DM, and obesity." (PMID 26056536, 2015). "On the other hand, HSD11B1 knockout mice exposed to a high fat diet are protected against the development of obesity and hyperglycemia." (PMID 26056536, 2015). "To elucidate this issue, we conducted a systematic review of the literature addressing the potential association of HSD11B1 polymorphic variants and abdominal HSD11B1 adipose tissue expression with MetS, type 2 diabetes mellitus (T2DM), and obesity." (PMID 26056536, 2015). "HSD11B1 enzymatic activities are thought to be involved in obesity, hypertension, and other components of the metabolic syndrome." (PMID 24658007, 2014). "This included protein kinase C elipson (PRKCE), known to be involved in brain tumors, carnitine palmitoyltransferase I (CPT1A), 11β-hydroxysteroid dehydrogenase type 1 (HSD11B1) and apolipoprotein B (APOB) which are all linked to obesity." (PMID 20502671, 2010). "Nevertheless, similarly to previous researchers, we observed an impact of obesity on the HSD11B1 expression between the visceral and subcutaneous depots: it was significantly higher in the VAT of normal-weight subjects, while in the course of obesity, its mRNA levels were higher in the SAT." (PMID 38791098, 2024). "It is reported that HSD11B1 can affects glucose uptake by adipocytes and leads to obesity in pig39." (PMID 38287039, 2024).
Obesity (continued). "Research indicates that individuals with obesity may exhibit reduced intra-abdominal expression of the VAT HSD11B1 gene, potentially as a compensatory mechanism to mitigate central and overall adiposity by lowering intra-abdominal cortisol levels." (PMID 39594522, 2024). "Additionally, HSD11B1 and HLA-DRA linked hypertension, diabetes, and obesity; UCHL1 linked hypertension, obesity, and lung cancer; LENG8 and HSPA1L linked diabetes, obesity, and lung cancer." (PMID 36685671, 2023). "Notably, HSD11B1 activity in adipose tissue is increased in individuals with obesity and hepatic HSD11B1 activity is decreased." (PMID 32069218, 2020). "Therefore, in the present study we investigated the potential synergistic effect of HSD11B1 (rs45487298:delA>insA) and H6PD (rs6688832:G>A) polymorphisms on obesity and MetS-related characteristics in white T2DM individuals." (PMID 31558916, 2019). "In this context, overexpression of the HSD11B1 gene might determine an increase in cortisol generation and, secondarily, generate pro-obesity effects." (PMID 31558916, 2019). "In addition, modulation of HSD11B1 activity has also an effect on multiple target tissues which promote insulin resistance independently of obesity." (PMID 31558916, 2019). "However, some reports found that inhibiting HSD11B1 via CBX causes glucose homeostasis problems and obesity." (PMID 26262685, 2015). "Another study found a significant risk of T2DM, but not of obesity, in Pima Indians with the HSD11B1 polymorphic variants rs846910 and rs12086634." (PMID 26056536, 2015). "Over-expression of Hsd11b1 in mouse liver also caused insulin-resistance, hypertension and fatty liver without obesity." (PMID 23533564, 2013). "Through the bioinformatics analysis, we identified HSD11B1, RXRG, G6PD, and PIK3R1 as core genes for the interplay between Crataegus pinnatifida and the obesity-related gut microbiota in obesity regulation." (PMID 41032481, 2025). "In contrast, liver-specific FGF21 knockout (FGF21 LKO) completely reversed OVX-induced high GCs and high visceral adipose Hsd11b1 expression, thus abrogating OVX-induced obesity in females." (PMID 37834368, 2023). "The abundance of transcripts of HSD11B1, HSD11B2, PER1, and NR3C1 were unaffected by obesity or insulin." (PMID 33270115, 2021). "In conclusion, our systematic review have shown that expression of the HSD11B1 gene in intra-abdominal adipose tissue is probably related to abnormalities of glucose metabolism, T2DM and obesity, with consistent findings across different studies." (PMID 26056536, 2015). "The positive correlation of genes such as HSD11B1, PTPN22, ABCC1, MMP9, FGF1, and F13A1 with M0 and M1 macrophages suggests a possible role in shaping the immune response toward a more beneficial phenotype in obesity." (PMID 39594522, 2024). "Furthermore, CDK5 and HSD11B1 are therapeutic targets of preclinical (L-751250) and Phase 1 (AZD8329) drugs for obesity, respectively, and our results provide genetic support for early stage development." (PMID 38167462, 2024). "At the same time, HSD11B1 and SLC2A4 may also be regulated by the corresponding lncRNA and miRNA, which ultimately affects glucose uptake by adipocytes and leads to obesity." (PMID 35456474, 2022). "To summarize, our results suggest that liver fat, rather than the degree of insulin resistance or obesity, influences hepatic HSD11B1 activity and GC metabolism." (PMID 32069218, 2020). "For example, in lean glucose-intolerant individuals, adipose HSD11B1 activity is not increased and hepatic HSD11B1 activity is maintained compared with the downregulation of hepatic HSD11B1 that occurs in obesity." (PMID 31558916, 2019). "While the literature suggests that HSD11B1 is hyperexpressed in abdominal adipose tissue in subjects with obesity and abnormal glucose metabolism, this seems to be not true for HSD11B1 gene expression and MetS." (PMID 26056536, 2015).
Obesity (continued). "In addition, Hsd11b1 null mice were resistant to HFD-induced insulin resistance, obesity and dyslipidaemia." (PMID 23533564, 2013). "In addition, another study showed that in some cases, the expression of HSD11B1 is lower in the VAT obtained from patients with obesity than from normal-weight patients, and that there is no regularity in this phenomenon." (PMID 38791098, 2024). "Additionally, HSD11B1 expression was analyzed in VAT and SAT in a different cohort of 28 participants with and without obesity who underwent elective abdominal operations." (PMID 31558916, 2019).